CXCR2 (C-X-C motif chemokine receptor 2)
Diseases named in the same sentence as CXCR2 in open-access papers (continued):
Sharing a sentence is not in itself a finding about the gene and the disease.
Stroke (13 papers, 2012 to 2025). Sudden impairment of blood flow to a part of the brain due to occlusion or rupture of an artery to the brain. "Our data prove that HPK1 increases neutrophil CXCR2 levels, contributing to neutrophil mobilization after stroke." (PMID 40169896, 2025). "In contrast, MG6 was defined as the “neutrophil-like” subset, with upregulated expression of Cxcr2, S100a8, Il1b, and Mmp9, perhaps representing a stroke-specific state of microglia in the aged brain after stroke." (PMID 36052339, 2022). "Multiple reports have suggested a role for aberrant CXCL1/CXCR2 signaling in adult CNS injury including stroke, traumatic brain injury (TBI), temporal lobe epilepsy, neuropathic nociception, central sensitization, and mechanical hypersensitivity." (PMID 31001130, 2019). "Therefore, HPK1 is involved in CXCR2 expression, accounting for neutrophil mobilization into the blood and infiltration into the brain and lungs after stroke." (PMID 40169896, 2025). "LRRK2, CALM1, CXCR4, TLR4, CTNNB1, and CXCR2 may be implicated in AF and the hub-genes of CD19, FGF9, SOX9, GNGT1, and NOG may be associated with stroke." (PMID 30760287, 2019). "The chemokine receptors CCR2, CCR5, CXCR2, CXCR3, CXCR4 and CX3CR1 are constitutively expressed in the human brain, and their expression is enhanced under pathological conditions, including stroke and neurodegenerative diseases like HIV-associated dementia (HAD) and Alzheimer’s disease (AD)." (PMID 23210607, 2012). "In addition, CXCR2 antagonism attenuated neurological deficits and infarct volumes via decreased cerebral neutrophil infiltration and peripheral neutrophilia in a hyperlipidemic ApoE−/− mice stroke model." (PMID 30760287, 2019). "In TBI and stroke, cerebral CXCL1/CXCR2 levels determine the magnitude of neutrophil infiltration, subsequent neuronal loss, and infarct volume." (PMID 31001130, 2019). "The CXCR2/CXCL8 axis is involved in chemotaxis of granulocytes and NK cells to the infarcted area after stroke." (PMID 31544811, 2019). "In the acute phase of stroke, targeted clearance or inhibition of neutrophil infiltration—via delivery of anti-Ly6G antibodies or blockade of CXC chemokine receptor 2 (CXCR2) and very late antigen-4 (VLA-4)—can significantly improve neurological deficits and reduce infarct volume." (PMID 41451205, 2025). "While it is known that CXCR2 is upregulated after stroke to recruit neutrophils to the brain, blocking CXCR2 does not necessarily improve neurofunctional outcomes." (PMID 37898992, 2024). "Repertaxin is a non-competitive allosteric inhibitor for CXCR2 and has been shown to be neuroprotective in rodent stroke models in two previous studies." (PMID 34983562, 2022). "Several chemokine receptors (eg CXCR1, CXCR2, CXCR3) are expressed in oligodendrocytes and show increased expression in MS, stroke and amyotrophic lateral sclerosis, and have been implicated in disorders in which myelin damage is associated with immune activation in the CNS." (PMID 29588250, 2018). "Among them, MG6 cells expressed high levels of Cxcr2, S100a8, interleukin (IL)‐1β, and matrix metallopeptidase 9 (MMP9), demonstrating a unique “neutrophil‐like” phenotype and were considered to represent a stroke‐specific state of microglia in the aged brain after stroke." (PMID 40843131, 2025). "As for CXCR2, anti-CXCR4 Nbs have been developed, but have not yet been tested in stroke." (PMID 31544811, 2019).
bladder cancer (12 papers, 2017 to 2024). "Several of the individual genes upregulated by Gardnerella exposures are involved in epithelial to mesenchymal transition (Cxcl5, Cxcr2, Tff1) or known to be elevated during squamous metaplasia or bladder cancer (Anxa10, Fosl1, Krt6a, Mmp10)." (PMID 35782131, 2022). "Recurrent bladder cancer cells exhibited similar levels of CXCR2 in comparison with the corresponding primary cancer cells." (PMID 28423359, 2017). "In bladder cancer, CXCL5 was found to be significantly upregulated and the CXCL5/CXCR2 axis could promote the migration and invasion of bladder cancer cells by activating the PI3K/AKT-induced upregulation of MMP2/MMP9." (PMID 29743818, 2018). "Furthermore, CXCR2 stimulation could promote bladder cancer cell migration and invasion by activating the PI3K/AKT-induced upregulation of MMP2/MMP9." (PMID 31681401, 2019). "To gain deeper insights into the regulatory effect of GRO-α-CXCR2 signaling on Snail functions, we examined the effect of GRO-α upon the subcellular localization of Snail in bladder cancer cells by scanning confocal microscopy." (PMID 28423359, 2017). "As the GRO-α receptor CXCR2 is expressed in all bladder cancer cells irrespective of the mesenchymal phenotype, it is probable that secretion of GRO-α is associated with bladder cancer recurrence via an autocrine loop involving its receptor." (PMID 28423359, 2017). "The purpose of this study was to assess the expression of CXCR2, IL-17RA, and IL-17RC genes at the mRNA level as well as tissue and serum levels of IL-17A, vascular endothelial growth factor (VEGF), and transforming growth factor β (TGF-β) in patients with bladder cancer (BC) compared to control." (PMID 38515019, 2024).
pneumonia (12 papers, 2005 to 2026). An acute, acute and chronic, or chronic inflammation focally or diffusely affecting the lung parenchyma, caused by an infection in one or both of the lungs (by bacteria, viruses, fungi, or mycoplasma.). "In conclusion, our data indicate that CXCR4 antagonism reduces pneumonia severity in a pharmacological mouse model of CXCR2 LOF, and this effect is likely associated with the normalization of neutrophil numbers in infected tissues." (PMID 41451234, 2025). "Severe pneumonia was associated with overexpression of cytokine transcripts activating the CXCR2 pathway, whereas patients with benign disease presented with a T helper “Th1-Th17” profile." (PMID 33780519, 2021). "Endothelial CXCR2 deficiency led to CXCR2 desensitization by decreased CXCR2 expression on neutrophils and subsequently impaired neutrophil migration 24 h after the induction of pneumonia." (PMID 40413164, 2025). "Overexpression of the A20 gene in ECs or pharmacological inhibition of CXCR2 on PMNs in iEC-Erg-/- mice rescued EC control of PMNs and tissue homeostasis, and enhanced mouse survival after pneumonia." (PMID 41785042, 2026). "Blocking CXCR2 can effectively reduce the aggregation of neutrophils in pneumonia mice and alleviate lung inflammation." (PMID 40540498, 2025). "The ability of the CXCR4 antagonist to reduce pneumonia in our CXCR2 LOF mice is likely related to its ability to mobilize neutrophils and facilitate their emigration into infected tissues rather than directly influencing neutrophil effector functions." (PMID 41451234, 2025). "The cell type-specific genetic deletion of CXCR2 in mice leads to impaired neutrophil recruitment and host defense against invading pathogens during bacterial-induced pneumonia." (PMID 40413164, 2025). "Other studies of inflammatory diseases, such as ventilator-induced lung injury, pneumonia, and hyperoxia-induced lung injury have demonstrated the importance of CXCR2 expression and its role in neutrophil recruitment during the pathogenesis of these diseases." (PMID 15921526, 2005). "Furthermore, our results demonstrate that CXCR4 antagonism reduces the severity of pneumonia in the CXCR2 LOF mice and facilitates the emigration of neutrophils into bacterially infected lung tissue." (PMID 41451234, 2025). "Additionally, CXCR4 antagonism mitigated the severity of pneumonia in CXCR2 LOF mice and facilitated neutrophil emigration into bacterially infected tissues." (PMID 41451234, 2025). "Furthermore, CXCR4 antagonism ameliorated the severity of pneumonia and facilitated the emigration of neutrophils into infected tissues in the CXCR2 LOF mice." (PMID 41451234, 2025). "CXCL5−/− mice do not show much decrease in CXCR2 expression on bone marrow and blood neutrophils as compared to the wild type (WT) mice upon E. coli-induced pneumonia, but the CXCR2 expression on neutrophils remains unchanged during intranasal lipopolysaccharide (LPS) challenge." (PMID 32849610, 2020). "Both CXCR1 and CXCR2 expression were up-regulated in all pneumonia samples." (PMID 31988368, 2020). "Moreover, phillyrin inhibited the mRNA and protein expression levels of Caspase1, ASC and NLRP3 in the lungs of mice with H1N1-induced pneumonia.This study reveals that phillyrin ameliorates IAV-induced pulmonary inflammation by antagonizing CXCR2 and inhibiting NLRP3 inflammasome activation partly." (PMID 37957672, 2023). "This study demonstrates that phillyrin can ameliorate pulmonary inflammation in mice with virus-induced pneumonia, and its anti-inflammatory mechanisms may be through antagonizing CXCR2 and suppressing NLRP3 inflammasome overactivation in the lung of infected mice." (PMID 37957672, 2023). "Therefore, CXCR2 may be an important drug-target of phillyrin against IAV-induced pneumonia." (PMID 37957672, 2023).
pneumonia (continued). "Some studies evaluated the prophylactic inhibition of neutrophils as a preventive treatment with G31P, an antagonist of CXCR2, which was shown to decrease neutrophil recruitment without affecting bacterial load in pneumonia induced by K. pneumoniae." (PMID 35682923, 2022). "To investigate a possible effect of CXCR2 knockout on CC chemokine homeostasis, we investigated trafficking of inflammatory monocytes in the lung in saline-treated control animals and after induction of pneumonia and did not observe significant differences." (PMID 40413164, 2025).
rheumatoid arthritis (12 papers, 2013 to 2025). A chronic, systemic autoimmune disorder characterized by inflammation in the synovial membranes and articular surfaces. "Interestingly, rheumatoid arthritis which is associated with CXCR2 deficiency is also associated with developing AMD later in life." (PMID 28769990, 2017). "Cxcl1, and its cognate receptor Cxcr2, are commonly associated with recruitment of neutrophils from the vascular supplies, and signaling via this receptor is implicated in the pathogenesis of rheumatoid arthritis, lung injury, and adenoviral keratitis." (PMID 25595590, 2015). "Studies with CXCR2-blockers and ligand-neutralizing agents in the context of different diseases (such as rheumatoid arthritis, COPD) are ongoing." (PMID 24339939, 2013). "Preclinical studies suggest that CXCR2 antagonists (e.g., navarixin), currently in Phase II trials for rheumatoid arthritis (NCT04000789), could be repurposed for OA patients with predominant inflammatory phenotypes." (PMID 40672822, 2025). "In rheumatoid arthritis, CXCR2 has been demonstrated in synovial-tissue macrophages." (PMID 23725043, 2013). "Several oral chemokine receptor antagonists, including CXCR2 and CXCR4 inhibitors, have been tried in human rheumatoid arthritis as well as in animal models of arthritis." (PMID 23725043, 2013).
triple-negative breast carcinoma (12 papers, 2019 to 2026). An invasive breast carcinoma which is negative for expression of estrogen receptor (ER), progesterone receptor (PR), and human epidermal growth factor receptor 2 (HER2). "Moreover, we have also shown that high expression of CXCR2 in triple negative breast cancers was also a predictor of a lower risk of relapse, which confirms the protective role of Cxcr2." (PMID 34070438, 2021). "Previous studies have shown that the chemokine receptor CXCR2 was expressed at higher levels by cells of the tumor microenvironment in triple-negative breast cancers (TNBCs)." (PMID 34066060, 2021). "The aim of this study was to focus on a retrospective cohort of triple-negative breast cancers (TNBCs) and analyze the involvement of CXCR2 and its link with immune infiltration and immune checkpoint markers." (PMID 34066060, 2021). "In the 4T1 murine tumor model of triple-negative breast cancer, CXCR2+ MDSCs are elevated in lung and lymph node metastases." (PMID 34944914, 2021). "We have previously shown that the ligands of the chemokine receptor CXCR2 were expressed at higher levels in triple-negative breast cancers (TNBC)." (PMID 32727083, 2020). "The CXCR2 has been used as a marker for triple-negative breast cancer." (PMID 35626430, 2022). "Furthermore, CXCR2 was expressed on G-MDSCs in the tumor microenvironment in the E0771-luciferase murine model of triple-negative breast cancer." (PMID 34944914, 2021). "Interestingly, high expression of CXCR2 was associated with higher-grade tumors but longer relapse-free survival and higher TIL infiltration in a cohort of triple-negative breast cancer patients treated with adjuvant chemotherapy." (PMID 34944914, 2021). "We, thus, hypothesize that the CXCR2/IL6 axis plays a synergistic role with FA2H in breast CSC signaling and, possibly and in particular, among triple negative breast cancers." (PMID 31709178, 2019). "In addition, we found that Shp1-mediated regulation of CXCR2 directly influences IL8-driven invasiveness in a subtype-specific manner, affecting luminal and triple-negative breast cancer (TNBC) cells but not HER2-positive ones." (PMID 41771840, 2026).
multiple sclerosis (11 papers, 2016 to 2023). A progressive autoimmune disorder affecting the central nervous system resulting in demyelination. "CXCR2 is expressed on endothelial cells, oligodendrocytes, and various immune cells; multiple sclerosis, traumatic brain injury, and Alzheimer’s disease are associated with CXCR2 and its ligands." (PMID 37445610, 2023). "Correspondingly, immunohistochemistry of brain biopsies from two patients with active multiple sclerosis revealed upregulation of endothelial CXCR2 compared to healthy control tissue." (PMID 30704100, 2019). "CXCL1 has been reported to be overexpressed in gastric, colon, and skin cancers and is known to recruit oligodendrocytes in multiple sclerosis when coupled with CXCR2." (PMID 27812125, 2016). "Cxcr2, a chemokine receptor on cellular surface, could upregulate and activate microglia in cerebral stoke, Alzheimer’s disease and multiple sclerosis." (PMID 35501920, 2022). "In experimental autoimmune encephalomyelitis (EAE), an animal model of multiple sclerosis, CerS6-deficiency enhances inflammation through increased infiltration of neutrophils as CerS6 was not able to counteract CD11b mediated activation and CXCR2-mediated migration." (PMID 29138469, 2017). "In addition, CXCR2 counteracts adult OPC differentiation and myelination potential, in a model of multiple sclerosis, by interfering with the PI3K/AKT/mTOR pathway, thereby strongly reinforcing the possibility of a role of cytokines and chemokines in OPC maturation blockade, during development." (PMID 36513635, 2022).
psoriasis (11 papers, 2015 to 2025). An autoimmune condition characterized by red, well-delineated plaques with silvery scales that are usually on the extensor surfaces and scalp. "The therapeutic response of IL-10 in psoriasis is associated with suppression of cutaneous inflammation, downregulation of the IL-8/CXCR2 pathway, and normalization of keratinocyte maturation." (PMID 38444844, 2024). "In support, treatment with a CXCR2 antagonist that blocks CXCL2-CXCR2 pathway for neutrophil recruitment significantly alleviated the pathogenesis of psoriasis caused by myeloid autophagy deficiency." (PMID 38704587, 2024). "The results of this study showed that CXCR2 was the potential gene target of the drugs for treating psoriasis." (PMID 32669126, 2020). "It has been shown that the expression of epidermal CXCR2 is increased in psoriasis, suggesting that activation of keratinocytes mediated by CXCR2 contributes to the characteristic epidermal changes observed in psoriasis." (PMID 32669126, 2020). "In the imiquimod-induced psoriasis model, LTB4-BLT1 signaling in neutrophils expedited their skin infiltration by cooperating with CXCR2 and intensified psoriasis development." (PMID 39859462, 2025). "Finally, PPI network analysis demonstrated that CXCL10 was the hub gene with the highest degree, and CXCR2, CXCL10, IVL, OASL, and ISG15 were the potential gene targets of the drugs for treating psoriasis." (PMID 32669126, 2020). "Besides, some psoriasis-related genes such as SPRR genes, HSD11B1, GGH, CXCR2, IVL, OASL, ISG15, and CXCL10 may be important targets in psoriatic therapy." (PMID 32669126, 2020).
injury (10 papers, 2012 to 2022). Damage inflicted on the body as the direct or indirect result of an external force, with or without disruption of structural continuity. "CXCR2 is upregulated in dorsal horn neurons after spinal nerve ligation, traumatic brain injury, and inflammation stimulation, which contribute to the maintenance of pain." (PMID 31681401, 2019). "IL-8 binds to G protein–coupled chemokine receptors (CXCR) 1 and CXCR2, which promote neutrophil influx into tissue sites of inflammation and induce acute lung injury." (PMID 25501580, 2014). "In fact, we confirmed here our earlier findings showing an increased mobilization of CXCR2-positive granulocytes in response to brain injury, compared with other surgical manipulations." (PMID 24478617, 2013). "A recently published study demonstrated that 12/15-LO-derived 12-HETE regulates vascular permeability in acute lung injury through a CXCR2-dependent mechanism." (PMID 22973824, 2012). "CXCL1/2 are major neutrophil chemoattractants that transduce signals by binding to the receptor, CXCR2 (56, –, 58), which mediates neutrophil recruitment and migration, as well as inflammation, in acute respiratory distress syndrome and acute lung injury (38, 54, –, 56, 59, 60)." (PMID 36005818, 2022). "In our previous study, induced pluripotent stem cells could downregulate neutrophil chemotaxis in endotoxin-induced acute lung injury, an effect associated with the enhancement of GRK2 activity and the reduction of CXCR2 expression." (PMID 32630825, 2020). "In the present study, we indicated that single and repeated intrathecal administration of CXCR2 (NVP CXCR2 20) and CXCR3 ((±)-NBI 74330) antagonists resulted in a strong and persistent dose-dependent analgesic effect 7 days after nerve injury in rats." (PMID 34681732, 2021). "A different situation was observed for the modulation of antinociceptive factors in the spinal cord of rats with nerve injury after (±)-NBI 74330 and NVP CXCR2 20 administration." (PMID 34681732, 2021). "Our results demonstrate that microglia reveal an early pro-inflammatory response demonstrated by an upregulation of CXCR2, CXCL1 and NLRP3 gene expression following LPS-sensitized HI brain injury in neonatal rats." (PMID 33123073, 2020). "We show here that very early granulocyte mobilization responses in response to brain injury are not dependent on CXCR2, and might not (or only in part) require the contribution of the bone marrow in the current experimental model." (PMID 24478617, 2013).